INKA2 (inka box actin regulator 2)
Description:
Inhibitor of the serine/threonine-protein kinase PAK4. Acts by binding PAK4 in a substrate-like manner, inhibiting the protein kinase activity.
Synonyms: C1orf183; FAM212B; FLJ31105
Tractability: No criterion of Open Targets' tractability assessment is met for any kind of drug.
Gene: Protein-coding gene on chromosome 1 (111,680,630 to 111,755,824, reverse strand). Ensembl gene ENSG00000197852.
Subcellular location: Nucleus
Subcellular location (Human Protein Atlas): Nucleoplasm; Nucleoli; Vesicles
Gene Ontology:
Molecular function: protein kinase binding; protein serine/threonine kinase inhibitor activity
Cellular component: nucleolus; nucleoplasm; nucleus
Genetic constraint (gnomAD): Loss-of-function variants: 9 observed, 16.87 expected, observed/expected ratio (o/e) 0.53, 90% interval 0.32 to 0.93. The upper end of that interval is the gene's LOEUF score, 0.93, which puts it in group 3 of 6, group 1 being the genes least tolerant of losing a copy. Missense variants: 392 observed, 403.54 expected, observed/expected ratio (o/e) 0.97, 90% interval 0.89 to 1.06. Synonymous variants: 147 observed, 152.49 expected, observed/expected ratio (o/e) 0.96, 90% interval 0.84 to 1.11.
Homologues: Orthologues: chimpanzee INKA2 (100% identical), macaque INKA2 (98% identical), guinea pig INKA2 (84% identical), pig INKA2 (81% identical), mouse Inka2 (80% identical), rat Inka2 (78% identical), rabbit INKA2 (76% identical), dog INKA2 (62% identical), tropical clawed frog inka2 (44% identical), zebrafish inka2 (35% identical). Paralogues in human: INKA1 (21% identical).
Diseases named in the same sentence as INKA2 in open-access papers:
INKA2 is named in the same sentence as 7 diseases in open-access papers, as found by Europe PMC text mining. Sharing a sentence is not in itself a finding about the gene and the disease. The quoted sentences say what the papers report.
melanoma (1 paper, 2022). A malignant, usually aggressive tumor composed of atypical, neoplastic melanocytes. "In humans, FAM212b (INKA2) expression level is correlated with increased melanoma metastasis and poor clinical outcomes in patients." (PMID 36301793, 2022).
cancer (1 paper, 2022). A tumor composed of atypical neoplastic, often pleomorphic cells that invade other tissues. "Inka1 was reported to serve as a Pak4 inhibitor in cancer cell lines; however, the physiological function of Inka2 is unclear." (PMID 36301793, 2022). "Besides cell-shape regulation, Inka2-mediated actin dynamics is closely related to various cellular processes, including cell migration, proliferation, cancer invasion, and adherent junction formation." (PMID 36301793, 2022).
tumor (1 paper, 2022). "Similar to the effect of Inka2 on tumor metastasis, Pak4 inhibitor PF-3758309 blocks the growth of multiple tumor xenografts." (PMID 36301793, 2022). "In addition, the direct interaction of Pak4 with Inka2-iBox is attributable to the anti-tumor effect of Inka2; however, the physiological function of Inka2 in neurons remains unclear." (PMID 36301793, 2022).
INKA2 also shares sentences with these, for which no sentence is quoted: breast cancer (2 papers); cleft lip (1); Crohn disease (1); pilocytic astrocytoma (1).